PHB1 (prohibitin 1)
Description:
Protein with pleiotropic attributes mediated in a cell-compartment- and tissue-specific manner, which include the plasma membrane-associated cell signaling functions, mitochondrial chaperone, and transcriptional co-regulator of transcription factors in the nucleus. Plays a role in adipose tissue and glucose homeostasis in a sex-specific manner (By similarity). Contributes to pulmonary vascular remodeling by accelerating proliferation of pulmonary arterial smooth muscle cells (By similarity). In the mitochondria, together with PHB2, forms large ring complexes (prohibitin complexes) in the inner mitochondrial membrane (IMM) and functions as a chaperone protein that stabilizes mitochondrial respiratory enzymes and maintains mitochondrial integrity in the IMM, which is required for mitochondrial morphogenesis, neuronal survival, and normal lifespan (Probable). The prohibitin complex, with DNAJC19, regulates cardiolipin remodeling and the protein turnover of OMA1 in a cardiolipin-binding manner (By similarity). Regulates mitochondrial respiration activity playing a role in cellular aging. The prohibitin complex plays a role of mitophagy receptor involved in targeting mitochondria for autophagic degradation. Involved in mitochondrial-mediated antiviral innate immunity, activates RIG-I-mediated signal transduction and production of IFNB1 and pro-inflammatory cytokine IL6. Interacts with STAT3 to affect IL17 secretion in T-helper Th17 cells. In the plasma membrane, cooperates with CD86 to mediate CD86-signaling in B lymphocytes that regulates the level of IgG1 produced through the activation of distal signaling intermediates (By similarity). Upon CD40 engagement, required to activate NF-kappa-B signaling pathway via phospholipase C and protein kinase C activation (By similarity).
Synonyms: PHB; BAP32; HEL-215; HEL-S-54e
Tractability: Antibody: UniProt places it where antibodies can reach, with high confidence; its Gene Ontology location is reachable by antibodies, with high confidence. PROTAC: ubiquitination databases record sites on it.
Gene: Protein-coding gene on chromosome 17 (49,404,009 to 49,414,905, reverse strand). Ensembl gene ENSG00000167085.
Subcellular location: Mitochondrion inner membrane; Nucleus; Cytoplasm; Cell membrane
Subcellular location (Human Protein Atlas): Mitochondria
Pathways (Reactome):
Disease: Paradoxical activation of RAF signaling by kinase inactive BRAF; Signaling by moderate kinase activity BRAF mutants; Signaling downstream of RAS mutants
Signal Transduction: RAF activation
Transport of small molecules: Processing of SMDT1
Gene Ontology:
Molecular function: complement component C3a binding; complement component C3b binding; enzyme binding; histone deacetylase binding; protein binding; protein heterodimerization activity; proteinase activated receptor binding; transcription corepressor activity
Biological process: antiviral innate immune response; cellular response to interleukin-6; epigenetic regulation of gene expression; mitochondrion organization; negative regulation of androgen receptor signaling pathway; negative regulation of cell growth; negative regulation of cell population proliferation; negative regulation of DNA-templated transcription; negative regulation of ERK1 and ERK2 cascade; negative regulation of nuclear receptor-mediated glucocorticoid signaling pathway; negative regulation of protein catabolic process; negative regulation of transcription by RNA polymerase II; osteoblast differentiation; positive regulation of complement activation; positive regulation of DNA-templated transcription; positive regulation of ERK1 and ERK2 cascade; positive regulation of G protein-coupled receptor signaling pathway; positive regulation of gene expression; positive regulation of interleukin-17 production; positive regulation of neuron apoptotic process; progesterone receptor signaling pathway; protein stabilization; regulation of DNA-templated transcription; RIG-I signaling pathway; T-helper 17 type immune response; and 9 more
Cellular component: cell surface; cytoplasm; early endosome; extracellular exosome; membrane; mitochondrial inner membrane; mitochondrial prohibitin complex; mitochondrion; nucleoplasm; nucleus; plasma membrane
Genetic constraint (gnomAD): Loss-of-function variants: 10 observed, 25.53 expected, observed/expected ratio (o/e) 0.39, 90% interval 0.24 to 0.66. The upper end of that interval is the gene's LOEUF score, 0.66, which puts it in group 2 of 6, group 1 being the genes least tolerant of losing a copy. Missense variants: 193 observed, 349.49 expected, observed/expected ratio (o/e) 0.55, 90% interval 0.49 to 0.62. Synonymous variants: 140 observed, 143.07 expected, observed/expected ratio (o/e) 0.98, 90% interval 0.85 to 1.13.
Homologues: Orthologues: chimpanzee PHB1 (100% identical), guinea pig PHB1 (100% identical), macaque PHB1 (100% identical), pig PHB1 (100% identical), mouse Phb1 (99% identical), tropical clawed frog phb1 (92% identical), zebrafish phb (92% identical), Drosophila melanogaster Phb1 (75% identical), rat AABR07037878.1 (75% identical), Caenorhabditis elegans phb-1 (66% identical). Paralogues in human: PHB2 (51% identical).
Diseases named in the same sentence as PHB1 in open-access papers:
PHB1 is named in the same sentence as 137 diseases in open-access papers, as found by Europe PMC text mining. Sharing a sentence is not in itself a finding about the gene and the disease. The quoted sentences say what the papers report.
breast carcinoma (31 papers, 2008 to 2025). "Two single nucleotide polymorphisms (SNPs) [rs3218550:NC_000007.14:g.152646870C>T, X-ray repair cross-complementing gene-2 (XRCC2)/7q36.1; and rs6917:NC_000017.11:g.49404181G>A, prohibitin-1 gene (PHB)/17q21.33] showed the strongest evidence for association with breast cancer risk." (PMID 30180900, 2018). "Furthermore, the presence of Single Nucleotide Polymorphisms (SNPs) in the PHB1–3’UTR (SNP rs6917) region has been associated with an increased risk of breast cancer and melanoma, whereas the rare allele of this SNP was associated with reduced PHB1 mRNA levels in gastric cancer." (PMID 29126391, 2017). "Elevated PHB1 is associated with increased metastasis in lung and prostate cancers, while both PHB1 and ANX2 have been implicated in breast cancer metastasis." (PMID 35991116, 2022). "In the MCF-7 and T47D breast cancer cell lines, PHB1 is mainly located in the nucleus; in the LNCaP prostate cancer cell line and the MG-63 osteosarcoma cell line, the presence of PHB1 staining in the nucleus was also noted." (PMID 26091791, 2015). "PHB1 co-localizes with transcription factors of the E2F family in the nucleus of breast carcinoma cells, and interacts with the Rb tumor suppressor protein pRB in the nucleus resulting in inhibition of the cell cycle." (PMID 20856874, 2010). "Correspondingly, siRNA-mediated silencing of PHB1 expression was found to increase breast cancer cell proliferation." (PMID 20856874, 2010). "However, in invasive and noninvasive breast cancer cells, PHB1 is mainly confined to the nucleus, in contrast to normal epithelial breast cells in which PHB1 is located primarily in the mitochondria." (PMID 26091791, 2015). "However, the export of PHB1 from the nucleus under camptothecin treatment in the breast cancer cell lines MCF-7 and T47D and the human fetal lung fibroblast cell line WI-38 is dependent on the protein exportin 1 (CRM1), a member of the importin family." (PMID 26091791, 2015). "In agreement with the initial finding that the RNA of 3′UTR of PHB1 exerts cytotoxic effects on cancer cells, the expression of a T-allelic PHB1 3′UTR has been linked with an increased susceptibility to breast cancer: however, several clinical studies have contradicted these findings." (PMID 20856874, 2010). "A T-allelic expression form of PHB1 was associated with an increased risk of breast cancer; however this association was not confirmed in a clinical setting." (PMID 20856874, 2010). "We have recently demonstrated in breast cancer cells, that progestin-activated PGRMC1 interacts with PHB1/PHB2 resulting in enhanced ERα-dependent transcription and cell proliferation." (PMID 38308254, 2024).
breast carcinoma (continued). "In human breast cancer cell lines, MCF-7 and T47D, PHB1 is mainly localized in the nucleus, but camptothecin treatment promotes its translocation from the nucleus to the mitochondria in response to apoptosis signal." (PMID 37210546, 2023). "Since PHB1 and PHB2 were reported to regulate ERα signaling, which is a central oncogenic pathway in luminal breast cancer, we focused on the implication of PGRMC1 in the ERα signaling network and its possible involvement in breast cancer promotion." (PMID 34830790, 2021). "To identify responsible factors that are involved in oncogenic signaling of HR positive breast cancer cells, we performed Co-IP with HA-PGRMC1 followed by mass spectrometry and identified PHB1 and PHB2 as possible PGRMC1 interaction partners upon treatment with NET." (PMID 34830790, 2021). "In breast cancer cell lines but not in normal cells, PHB1 is mainly localized in the nucleus and can be exported in response to a topoisomerase 1 inhibitor, camptothecin, in a CRM-1-dependent manner." (PMID 24709813, 2014). "In recent years, a large number of studies have shown that PHB1 expression is upregulated in a variety of human malignancies, including lung cancer, diffuse large B-cell lymphomas (DLBCL), cervical cancer, bladder cancer, glioblastoma, endometrial cancer, and breast cancer, etc.." (PMID 37210546, 2023).
prostate cancer (15 papers, 2008 to 2025). A primary or metastatic malignant tumor involving the prostate gland. "Another study reported that cholesterol insufficiency in prostate cancer cells causes up-regulation of PHB1, inducing cell cycle arrest and apoptosis." (PMID 29784973, 2018). "In prostate cancer, nuclear Phb1 has been reported to regulate cell cycle progression targeted by androgen." (PMID 35668443, 2022). "A clear tumour suppression role of PHB1 has been demonstrated in breast, gastric and prostate cancers." (PMID 30886235, 2019). "In androgen-independent prostate cancer cells, estrogen activates ERα and promotes mitochondrial-nuclear PHB1 translocation, leading to cancer cell resistance to paclitaxel." (PMID 26091791, 2015). "Similarly, in prostate cancer and gastric cancer cells, microRNA-27a promotes tumor growth by directly targeting PHB1." (PMID 26091791, 2015). "In prostate cancer cells, TGF-β activation of the Raf-MEK-ERK-PKC-δ intracellular signal pathway leads to PHB1 phosphorylation and decreases inner mitochondrial permeability, cell survival, and cell invasion." (PMID 26091791, 2015). "In androgen-sensitive and TGF-β-responsive human prostate cancer cells, TGF-β treatment promoted PHB1 export from the nucleus to the cytosol, which preceded apoptotic cell death." (PMID 26091791, 2015).
colorectal cancer (11 papers, 2011 to 2025). A primary or metastatic malignant neoplasm that affects the colon or rectum. "In addition, some cancers (colorectal cancer) are associated with a marked increase in PHB1 and PHB2 levels in blood serum." (PMID 38813101, 2024). "Some researches claimed that a polarized distribution of PHB1 in cells controls the migration direction of colorectal cancer cells." (PMID 29784973, 2018). "PHB1 can relocate to the luminal side of cells, face extracellular VEGF and indicate the direction of colorectal cancer cell invasion." (PMID 29784973, 2018).
ileitis (11 papers, 2021 to 2025). "Further, mitochondrial dysfunction linked to ablation of prohibitin 1 in IECs preceded spontaneous ileitis with abnormalities in PCs functions." (PMID 38839896, 2024). "The role of Paneth cell mitochondrial impairment in the development of ileitis has been documented in multiple studies on PHB1-deficient mice." (PMID 39840057, 2024). "In the present study, we investigated the role of the mitochondrion-microbiome axis in mouse models of spontaneous ileitis driven by the loss of Phb1 expression." (PMID 37978573, 2023). "Depleting gut microbiota by ABX protected Phb1-deficient mice from spontaneous ileitis measured histologically and from proinflammatory cytokine expression upregulated in these mouse models." (PMID 37978573, 2023). "Deletion of Phb1 specifically in Paneth cells (Phb1∆PC mice) was sufficient to induce Paneth cell defects and to cause ileitis in mice." (PMID 37978573, 2023). "Supplementation of butyrate in Phb1-deficient mice ameliorated Paneth cell abnormalities and ileitis." (PMID 37978573, 2023). "Paneth cell-specific deletion of Phb1 driven by Defα6-Cre or Mist1-CreERT2 was sufficient to drive spontaneous ileitis, suggesting a causative role of mitochondrial dysfunction in ileitis that initiates in Paneth cells." (PMID 34072441, 2021). "identify Paneth cells as highly susceptible to mitochondrial dysfunction driven by loss of prohibitin 1 (PHB1), a major component protein of the inner mitochondrial membrane, and central to the pathogenesis of ileitis." (PMID 34326845, 2021). "Mitochondrial impairment due to a deficiency of prohibitin 1, a mitochondrial chaperone protein required for optimal electron transport chain function, promotes the development of ileitis in conjunction with changes in the gut microbiota, and restoration of butyrate prevents ileitis." (PMID 40821844, 2025). "Mice deficient in PHB1 in Paneth cells (epithelial secretory cells of the small intestine; Phb1∆PC) also exhibited mitochondrial impairment, Paneth cell defects, and spontaneous ileitis." (PMID 37978573, 2023). "It has been reported that targeted deletion of the Phb1 or Hsp60 gene in IECs causes defects in PCs primarily by disrupting mitochondrial function, which compromises the epithelium–host defense and is the central to the pathogenesis of ileitis." (PMID 37696579, 2023). "Jackson et al63 showed that deletion of prohibitin-1 (Phb1), a gene encoding a major component protein of the inner mitochondrial membrane protein, caused mitochondrial dysfunction and clinical spontaneous murine ileitis." (PMID 37094358, 2023). "Mitochondrial dysfunction in intestinal epithelial cells, induced by PHB1 deletion was found to trigger spontaneous ileitis in mice." (PMID 39840057, 2024). "Targeted deletion of the genes encoding mitochondrial proteins prohibitin 1 (PHB1) and heat shock protein 60 (HSP60) in mice results in PC defects and causes a predisposition to ileitis in mice." (PMID 37696579, 2023). "Deletion of PHB1 specifically in Paneth cells driven by Defα6Cre or Mist1CreERT2 (Phb1∆PC) was sufficient to induce Paneth cell defects and ileitis in mice." (PMID 37978573, 2023). "A specific role of Paneth cell mitochondrial dysfunction in driving ileitis was demonstrated using mice with Paneth cell-specific deletion of PHB1." (PMID 37443813, 2023). "Taken together, these data demonstrate the therapeutic potential of butyrate on Paneth cell abnormalities and ileitis driven by epithelial mitochondrial dysfunction during Phb1 deletion." (PMID 37978573, 2023). "Our recent study in mice demonstrated that the induction of mitochondrial dysfunction by deletion of Phb1 in intestinal epithelial cells triggered Paneth cell abnormalities and spontaneous ileitis in mice." (PMID 34072441, 2021).
ileitis (continued). "HuR ablation in mice decreased the levels of PHB1 and HSP60; these two proteins are essential for mitochondrial integrity in the intestinal epithelium and loss of PHB1 or HSP60 results in defective PCs and leads to ileitis in mice." (PMID 37696579, 2023). "We previously demonstrated that mice deficient in PHB1 specifically in IECs (Phb1i∆IEC) exhibited mitochondrial impairment, Paneth cell defects, gut microbiota dysbiosis, and spontaneous inflammation in the ileum (ileitis)." (PMID 37978573, 2023). "It was found that PHB1 protein was downregulated in patients with IBD, and the specific knockout of PHB1 in intestinal epithelial cells leads to mitochondrial dysfunction of intestinal epithelial cells and Paneth cell dysfunction, inducing spontaneous ileitis in mice." (PMID 36348375, 2022). "The specific knockout of PHB1 in Paneth cells can also induce ileitis." (PMID 36348375, 2022). "Using germ-free mice colonized with ileal microbiota from Phb1-deficient mice, we show that this microbiota could not independently induce ileitis without host mitochondrial dysfunction." (PMID 37978573, 2023). "Ileal microbiota were used as donor material since our mouse models of Phb1 deletion develop ileitis without affecting the colon." (PMID 37978573, 2023). "In addition, absence of prohibitin 1 (Phb1), a critical inner mitochondrial membrane protein, in intestinal epithelium led to the development of spontaneous ileitis in mice." (PMID 38839896, 2024).
gastric cancer (10 papers, 2014 to 2025). A primary or metastatic malignant neoplasm involving the stomach. "Overexpressed SLP2 competed against E3 ubiquitin ligase SKP2 to bind with PHB1 and decreases the ubiquitination level of PHB1, causing gastric cancer progression, and the authors attributed to SLP-induced activation of the MAPK signaling pathway." (PMID 36348375, 2022). "In one study, researchers found that in gastric cancer, the microRNA miR-27a is upregulated, targets PHB1, and acts as an oncogene." (PMID 34868199, 2021). "Downregulating miR-27a in these gastric cancer cells increased levels of PHB1 protein and transcripts." (PMID 34868199, 2021). "Western blot analysis of clinical samples showed that the expression of PHB1 protein in gastric cancer tissues was significantly higher than that in adjacent tissues (p < 0.05)." (PMID 34122065, 2021). "Intriguingly, knockdown of PHB1 increased cancer cell apoptosis in SGC7901 cells, but overexpression of PHB1 increased apoptosis in BGC823 cells, and both lines are gastric carcinoma cells." (PMID 26091791, 2015).